TNF (tumor necrosis factor)
Diseases named in the same sentence as TNF in open-access papers (continued):
Sharing a sentence is not in itself a finding about the gene and the disease.
diabetes (continued). "While salivary TNF-α has great promise for use as of much value, there are scanty reports about the level of salivary TNF-α in diabetes-associated OSCC." (PMID 38406163, 2024). "Hesperidin demonstrated neural protective effects, which are evident from decreased neutrophil and macrophage infiltration in the sciatic nerve and decreased mRNA expression of neural TNF-α and IL-1β, two key pro-inflammatory cytokines in diabetes progression." (PMID 39459367, 2024). "Although this study is a significant contribution to understanding the relationship between TNF-α in oral carcinogenesis and its relation to diabetes, several limitations should be discussed." (PMID 38406163, 2024). "Elevated levels of pro-inflammatory cytokines, including IL-1β, IL-6, and TNF-α, are often observed in diabetic mellitus patients." (PMID 39050988, 2024). "Our study showed that diabetes led to increased TNF-α, IFN-γ, and IL-1β levels, whereas intravitreal injection of porous Se@SiO2 nanospheres decreased the levels of these cytokines in db/db mice." (PMID 38321393, 2024). "Recent experimental data indicate a decrease in serum levels of TNF-α by O. acanthium in rats with streptozotocin-induced diabetes." (PMID 39683190, 2024). "In terms of SCFAs, for flaxseed oil exerted anti-diabetes action on streptozotocin-nicotinamide-induced rats, the acetic acid was negatively correlated with TNF-α, IL-1β, IL-6, and IL-17A." (PMID 39403395, 2024). "Like astaxanthin, it was found that metformin (used as a first-line therapy for type 2 diabetes mellitus) can decrease the cellular level of NF-κB which leads to decreasing the cellular levels of TNF-α, IL-1β, and IL-6." (PMID 39693313, 2024). "In our study, at the end of treatment, compared with MIRI of diabetes group, the myocardial TNF-α and IL-6 levels in treatment group were significantly decreased." (PMID 38422326, 2024). "Previous studies also have reported serum up-regulation of TNF-α levels in human and experimental animal models of diabetes." (PMID 38227584, 2024). "During the early stages of diabetes, immune cells infiltrate the pancreas and produce proinflammatory cytokines, such as IL-1, IFNα/γ, and TNFα." (PMID 39159002, 2024). "The role of TNF in diabetes complications has already been elucidated; for example, increased TNFα levels have been observed in tear samples of diabetic patients, which has also been shown to correlate with retinopathy and nephropathy severity." (PMID 38842591, 2024). "Systemic inflammation caused by pro-inflammatory cytokines in periodontitis like IL-6 and TNF-α contributes to cardiovascular disease, diabetes, and metabolic syndrome." (PMID 39795606, 2024). "TNF‐α levels were statistically significantly higher in diabetic group than in control, 2 mg/kg bW stevia, 25 mg/kg bW stevia, and diabetes +25 mg/kg bW stevia groups (***p < .001)." (PMID 39479688, 2024). "Apart from classical inflammatory cytokines (such as TNF, IL1, or IL6), new markers of inflammation have arisen as important pathogenic mediators for the progression of chronic kidney disease in diabetes (i.e., IL-1 beta, caspase 1-dependent NLRP3)." (PMID 38921685, 2024). "The improved expression of Ang-2 has led to the development of endothelial microvascular cells more prone to anti-inflammatory actions of tumor necrosis factors alpha (TNF) in kidneys and cells of patients with diabetes mice." (PMID 39674630, 2024). "Higher expression of proinflammatory factors such as IL-1β, IL-6, and TNF-α and accumulation of AGEs in a diabetes-induced inflammatory environment can all harm the BBB." (PMID 38645427, 2024). "Diabetes reduced the IL-10, IL-11, and Nrf2 levels (P<0.001 to P<0.01) and increased the levels of TNF-α and NF-κB compared to the Col group (P<0.001)." (PMID 38164478, 2024). "TNF‐α level was statistically significantly higher in diabetes and diabetes +2 mg/kg bW stevia groups compared to control, 2 mg/kg bW stevia, 25 mg/kg bW stevia, and diabetes +25 mg/kg bW stevia groups." (PMID 39479688, 2024).
diabetes (continued). "Regarding the group with diabetes, at baseline (T0), it was evidenced positive significant correlations both between circulating levels of TNF-α and IL-6, and between levels of IL-10 and EMP, as well as a negative significant correlation between IL-10 and PMP." (PMID 39253540, 2024). "In diabetes, TNFα and 1L-1ß are moderately correlated (r2 = 0.59, p = 0.001) but their association is less correlated (r2 = 0.32, p = 0.0103) with PCI patients without diabetic complications." (PMID 38216681, 2024). "Present study revealed that diabetes increased TNFα as a pro-inflammatory cytokine and reduced IL-10 as an anti-inflammatory cytokine in BALF." (PMID 38233819, 2024). "In present study, inflammatory cytokines such as IL-6, IL-8 and TNF-α were assayed to assess the impact of diabetes on immunological responses." (PMID 38933114, 2024). "We explored the potential effects of ART, known for its anti-inflammatory, antifibrotic, and blood glucose-lowering properties of ART on the NF-κB/ TNF-α signaling pathway to improve dry eye in rats with diabetes." (PMID 38821986, 2024). "Secondly, another research showed increased concentrations of TNF-α in diabetes patients suggesting the possibility of communication between disease processes." (PMID 38406163, 2024). "TNF-α levels were significantly increased in participants who had hypertension, diabetes, hyperlipidaemia and/or were taking statins or calcium channel blockers." (PMID 39186241, 2024). "The level of TNF-α immune factor is closely related to tumours, diabetes, and especially autoimmune diseases." (PMID 38540831, 2024). "Mechanistically, diabetes induction resulted in kidney inflammation by elevating levels of tumor necrosis factor-alpha (TNF-α), transforming growth factor beta (TGF-β), and interleukin 6 (IL-6), while reducing IL-10 levels and increasing the IL-6/IL-10 ratio." (PMID 38510054, 2024). "In the early stages of diabetes, glomerular and tubular cells have increased expression of tumor necrosis factor (TNF) α, interleukin (IL)-6, IL-1, and adhesion molecules." (PMID 38674089, 2024). "The inflammation that occurs in adipose tissue due to the release of TNF-α, IL-1β, and IL-6 is a crucial factor in the development of cardiovascular disorders, diabetes, and cancers." (PMID 38317220, 2024). "In diabetes mellitus, the increase in glucose levels is correlated with the increased recruitment of macrophages followed by the intensification of the secretion of TNF-α and cytokines." (PMID 39596058, 2024). "Diabetes can accelerate vascular aging through inflammatory responses that lead to elevated production of cytokines such as tumor necrosis factor-α (TNF-α) and interleukin (IL)-6." (PMID 39123214, 2024). "Our research found increased levels of TNFα in the serum of individuals affected by both periodontitis and diabetes." (PMID 38920850, 2024). "Under inflammatory conditions like diabetes and periodontitis, cytokines such as TNF-α, IL-1, and PGE2 enhance osteoclast formation and activity via RANK signalling in osteoclast progenitors." (PMID 38614881, 2024). "This body of research underscores the complex impact of anti-TNF treatments on glucose metabolism, suggesting a potential link between AS management strategies and the development of diabetes." (PMID 39649224, 2024). "We observed a significant correlation between high TNF-α levels and diabetes among the participants." (PMID 39149648, 2024). "An experimental study demonstrated that moderate and regular exercise training reduces CRP, IL-6, TNF-α and increases adiponectin levels and IL-10.In general, exercise has anti-inflammatory effects especially in diabetes." (PMID 38233819, 2024). "They act via the AGE receptor (RAGE) triggering the activation of NF-κB signaling, as shown in murine models in which diabetes increased cytosolic levels of ROS, RAGEs, Tumor Necrosis Factor alpha (TNF-α) and nuclear levels of NFkB-p65 in cardiomyocytes." (PMID 39125850, 2024).
diabetes (continued). "Our study measured four inflammation-related markers such as COX-2, PGE-2, TNF-α, and NF-κB, all of which were elevated following diabetes induction, reflecting an inflammatory state in neural tissue." (PMID 39766390, 2024). "Two, characterizing serum and plasma markers (resorption CTX, formation P1NP, sclerostin, insulin, insulin-like growth factor 1, IL-6, TNFα, etc.)would identify potential metabolic pathways by which diet and diabetes lower the fracture resistance of bone." (PMID 39012489, 2024). "In terms of inflammation pathways, chronic inflammation markers such as high-sensitivity CRP, IL-6, and TNF-α have been shown to be elevated prior to the onset of diabetes." (PMID 38188453, 2024). "Patients who have diabetes or are obese experience persistent, mild inflammation characterized by elevated levels of inflammatory markers such as tumor necrosis factor alpha (TNF-α) and C-reactive protein (CRP)." (PMID 39031306, 2024). "TNF-α levels are directly related to the weight and body mass index (BMI) of patients with diabetes and are greater in obese people." (PMID 39596058, 2024). "Proinflammatory conditions produced by diabetes induce Interleukin-6 (IL-6), Tumor Necrosis Factor-α (TNF-α), and other chronic inflammatory markers." (PMID 38611003, 2024). "Diabetes was associated with increased angiogenesis through an increase in VEGF, TGF-β, FGF-21, TNF-α and NO levels and a decrease in FLK-1 and sFLT-1 levels." (PMID 38584657, 2024). "Hub gene and TNF signaling pathway are helpful to elucidate the molecular mechanism of the bidirectional relationship between periodontitis and diabetes." (PMID 37986309, 2023). "Adiponectin (APN) plays a role in anti-inflammation via the inhibition of TNF-α, VCAM-1, and ICAM-1, and a low level has been associated with increased diabetes risk." (PMID 37092467, 2023). "This study showed that 12 weeks of oral treatment of TRF in rats with STZ-induced diabetes reduces expression of the markers of retinal inflammation including IL-1β, IL-6, TNF-α, IFN-γ, MCP-1, and iNOS." (PMID 37268913, 2023). "Of the different inflammatory parameters analyzed, including inflammatory cytokines, hs-PCR, and NLR, only TNFα differed between groups, presenting higher values in the group of patients with diabetes (1.99 [1.38–2.67] vs. 2.2 [1.59–2.99] pg/mL, p < 0.01)." (PMID 37762433, 2023). "HIV, diabetes, malnutrition, biological therapy based on TNF-α inhibitors, extreme age (children below 5 age or elderly)." (PMID 37662901, 2023). "We performed a randomized crossover trial to investigate the impact of daily consumption of InsP6 on serum levels of adiponectin, TNF-alpha, IL-6, and IL-1beta in patients with type 2 diabetes mellitus (T2DM; n = 39)." (PMID 36854678, 2023). "Diabetes condition increases inflammation, this is in accordance with our study, which showed an increase in the expression of IL-6 and TNF-a in inflammatory cells." (PMID 36599453, 2023). "In an age-matched group of patients with diabetes, as well as some with diabetes and retinopathy, they showed that TNF-α was the most important predictor of vision damage." (PMID 37893230, 2023). "Similar activity and decreased levels of TNF-α, IL-1β, and IL-6 in serum were reported for fucoidan isolated from Saccharina japonica in a model of streptozotocin-induced diabetes mellitus in rats after 4 weeks of treatment." (PMID 37760952, 2023). "The diabetes + saline treatment group exhibited significantly higher levels of TNF-α in the sciatic nerve (48.5 ± 1.7 pg/mg) compared to the control group (26.2 ± 2.08 pg/mg) (p < 0.001)." (PMID 38055406, 2023). "A 2 g intake of FO for the 14-week period tended to decrease fasting blood glucose, C reactive protein, and TNF-α levels in overweight adults with pre-diabetes." (PMID 37685162, 2023).
diabetes (continued). "Lastly, there was a search done with specific overlaps, such as the role of IL-1b in both diabetes and OA, with specific keywords such as interleukin-1 (IL-1), tumor necrosis factor (TNF) alpha, and oxidative stress." (PMID 37255905, 2023). "Metabolic syndrome, dyslipidemia, and diabetes induce continuous TNF-α production, inducing chronic inflammation in the blood vessels and the onset of atherosclerosis." (PMID 36768946, 2023). "Most previous studies on the association of protein supplementation with proinflammatory cytokines have focused on healthy older adults, diabetics, or sarcopenic obesity, where the impact on IL-6 and TNF-α has been variable." (PMID 37644985, 2023). "Protein lysates of individual retinas (n = 9/group) were collected for automated Ella quantification of IL-1β, IL-6, and TNF-α; 2 months after diabetes was confirmed." (PMID 36674854, 2023). "Another investigation performed in adoptive transfer models suggested that TNF-α plays a crucial role in Th1 and Th2 cells during diabetes induction." (PMID 37189738, 2023). "Periodontal disease has been associated with higher levels of inflammatory mediators such as TNF-α in people with diabetes." (PMID 36981453, 2023). "In contrast to what was observed in the hippocampus, the relative mRNA expression of TLR4 and TNFα in the cerebral cortex was significantly increased by short-term diabetes." (PMID 36674713, 2023). "Patients with ILD were more likely to receive non-TNF inhibitors than JAKis (OR 0.21, CI 0.06–0.72), but the reverse was true for patients with diabetes mellitus (OR 5.00, CI 1.24–20.22)." (PMID 36626396, 2023). "Diabetes augmented levels of AGEs (A), ET-1 (B), TNF-α (C), iNOS (D,E), which appeared to be significantly (p ≤ 0.001) but not completely inhibited by metformin." (PMID 36830898, 2023). "Only TNF-α differed between healthy and diabetes cohorts, with increased levels compared to type 1 (p = 0.049) and decreased levels compared to type 2 (p = 0.008)." (PMID 37189645, 2023). "Recently, QUET was shown to reduce diabetes-induced neuroinflammation by inhibiting astrocyte and microglia activation, as well as by lowering TNF-α and monocyte chemoattractant protein-1 (MCP-1) levels in the mouse hippocampus and cerebrospinal fluid." (PMID 37511284, 2023). "Numerous controlled human studies demonstrate that successful periodontal treatment reduces circulating C-reactive protein (CRP) and tumor necrosis factor (TNF)-α levels in subjects with diabetes, proving its active role in inflammation." (PMID 36832168, 2023). "The inflammatory mediators TNF-α, IL-1β, IFN-γ, iNOS and NF-κB have close association with progression of diabetes." (PMID 36653816, 2023). "Blackberry juice significantly (p < 0.05) reduced increased hepatic TNF-α and IL-6 by about 65% and 69%, respectively, in rats with diabetes in comparison to only rats with diabetes." (PMID 37280499, 2023). "Possible mechanisms linking periodontal disease to diabetes mellitus include elevated systemic levels of pro-inflammatory cytokines, especially interleukin‐1, interleukin‐6 and tumor necrosis factor alpha." (PMID 36138236, 2023). "Patients with coverageBASE below 16.85% were found to have higher levels of VEGF and TNF-α, as well as higher levels of HbA1c during the first two years following diabetes diagnosis." (PMID 37893230, 2023). "In diabetes, proinflammatory cytokines, such as TNF-α, IL-1, and IL-6, activate inflammatory signaling pathways, which lead to cardiac fibrosis, hypertrophy, cell death, systolic and diastolic dysfunction, and finally heart failure." (PMID 38069059, 2023). "It is noteworthy that diabetes is characterized by a pro-inflammatory state, marked by chronically elevated levels of tumor necrosis factor α (TNF-α), transforming growth factor β (TGF-β), and interleukin-6 (IL-6)." (PMID 38137522, 2023).
diabetes (continued). "A review identified that arsenic plays a role in inducing diabetes by altering tumor necrosis factor-α (TNF-α), GLUT4 and mitogen-activated protein kinase (MAPK)." (PMID 37240215, 2023). "Diabetes augments levels of inflammatory cytokines such as TNF-α, interleukin-1β (IL-1β), interleukin-17 (IL-17), interleukin-23 (IL-23), and interleukin-6 (IL-6) in human periodontal tissue." (PMID 36875028, 2023). "gingivaliscan produce apical periodontitis in diabetes mellitus rats in anin vivomodel, and affect the expression of IL-6 and TNF-a." (PMID 36599453, 2023). "The clinical (BOP) and glucose parameters (fasting glucose levels, and HbA1c) were statistically higher in the diabetes group; moreover, RNAm levels of IL-1β, TNF-α, and NF-kB were higher when compared to healthy controls." (PMID 36832168, 2023). "The overexpression of cytokines IL-1β, IL-6, and TNF-α is known to affect systemic acute inflammatory syndrome, chronic immune disease, pain, cardiovascular disease, and diabetes." (PMID 37764215, 2023). "DEXA+ MET association reduced the inflammation profile of TNF-α and IL-6, results explained by the anti-inflammatory role of MET in diabetes mellitus." (PMID 37894792, 2023). "Interleukins (ILs) and tumor necrosis factor-α (TNF-α) are pro-inflammatory molecules whose circulating levels have been shown to be elevated in diabetes." (PMID 37092467, 2023). "A correlation between diabetes and increased concentrations of inflammatory compounds such as TNF-α has been observed in those with neuropathic afflictions." (PMID 37189822, 2023). "A massive amount of TNF-α production suppresses GLUT4 production and leads to the development of insulin resistance, causing diabetes, atherosclerosis, liver failure, and dementia." (PMID 37569540, 2023). "Comorbidities like hypertension, diabetes, and hyperlipidemia share common inflammatory pathways involving inflammatory cytokines such as tumor necrosis factor (TNF)." (PMID 37894979, 2023). "Successful periodontal treatment has been shown to lower the circulating levels of C-reactive protein (CRP) and tumor necrosis factor (TNF)-α in people with diabetes, providing further evidence of its active role in inflammation." (PMID 38132485, 2023). "Data supporting diabetes-induced microglial phenotype in db/db mice include IL-1β and TNF-α upregulation in the cortex and hippocampus of these mice; as well as higher secretion levels of IL-1β, IL-6, TNF-α and MCP-1 by isolated forebrain mononuclear cells." (PMID 36869375, 2023). "TNFα levels were increased in the small intestine and decreased in colonic ganglia in response to diabetes similarly to TLR4 expression." (PMID 36672637, 2023). "Mechanistically, this was related to the level of inflammation as shown by the rescue of diabetes-reduced neovascularization when a TNFα-specific inhibitor, pegsunercept (PEG), was applied." (PMID 37576976, 2023). "The TNF-α/IL-35 ratio correlated significantly with HbA1c at the time of diabetes onset (r = 0.52, p < 0.001), as well as with HbA1c after 1 year (r = 0.38, p = 0.009)." (PMID 37893230, 2023). "In contrast, both Rilmenidine-treated groups showed reduced TNF-α levels: diabetes + 0.1 mg/kg Rilmenidine group (33.1 ± 0.9 pg/mg), and diabetes + 0.2 mg/kg Rilmenidine group (30.3 ± 0.5 pg/mg)." (PMID 38055406, 2023). "Treatment with quercetin largely inhibited SARS-CoV-2 N protein-induced F4/80+ macrophages infiltrating the diabetic kidney and greatly suppressed the mRNA expression of IL-6, TNF-α, and MCP-1 while increasing the expression of IL-4 and IL-10 mRNA levels." (PMID 38022581, 2023). "Another major limitation of this meta-analysis is that there is only one study that evaluated the association between serum TNF-α levels and the risk of DPN in type 1 diabetes mellitus." (PMID 38179375, 2023). "Aging and some comorbidities, such as diabetes, are low-grade inflammatory states with increased levels of proinflammatory markers (IL-6 and TNF-α)." (PMID 37003999, 2023).